BRAF (B-Raf proto-oncogene, serine/threonine kinase)
Diseases named in the same sentence as BRAF in open-access papers (continued):
Sharing a sentence is not in itself a finding about the gene and the disease.
melanoma (continued). "For patients with advanced melanomas harboring BRAF mutations, combination treatment with BRAF-MEK inhibitors has shown promising outcomes." (PMID 39534873, 2024). "Somatic mutations in key melanoma oncogenes, such as BRAF or NRAS, are already present in benign nevi, indicating that they occur early during disease progression." (PMID 38396984, 2024). "It is clear from our results that immunotherapy should be strongly considered (as clinically appropriate) as the first-line therapy for patients with advanced melanoma bearing a BRAF mutation." (PMID 38473384, 2024). "To further validate the involvement of ATP1A1 in resistance to BRAF-targeted therapy, we conducted experiments using three different models of melanoma cell lines (harbouring mutations in cKIT, BRAF or NRAS)." (PMID 38178183, 2024). "BRAF inhibitors, such as vemurafenib and dabrafenib, are effective treatments for melanoma with BRAF mutations." (PMID 39329914, 2024). "This efficacy was observed in melanoma cells carrying BRAF as well as N-Ras mutation, namely SK-MEL-28 and SK-MEL-2, suggesting that the ERK pathway is the point more crucial than the Akt pathway for the treatment with EVs (Amnio and Cesarean)." (PMID 39684214, 2024). "While advanced melanoma patients with BRAF mutations have increased risk for BrM, those patients with BrM who are BRAF mutation-positive have a better survival than BrM patients who are mutation-negative." (PMID 38730723, 2024). "Remarkably, PLA1A levels exhibit a significant elevation during melanogenesis, particularly in BRAF-mutated melanoma cases." (PMID 39582535, 2024). "Subsequent studies showed that BRAF mutation frequency ranges from 28 to 54% of analyzed melanoma samples depending on the analyzed group of patients, biological material, and technique." (PMID 39340537, 2024). "In a cohort of 210 advanced melanoma patients, those with positive PD-L1 expression (>1%) and BRAF V600 mutations demonstrated significantly higher survival rates after ICI therapy compared to patients without these biomarkers." (PMID 39200315, 2024). "Melanomas that have mutations other than BRAF V600E, such as RAS mutations or non-V600 BRAF mutations, do not exhibit a positive response to BRAF inhibitors." (PMID 38534309, 2024). "Different cellular models of melanoma becoming resistant to BRAF inhibitors were found to harbor BRAF mutations and numerous growth factor pathway alterations." (PMID 38255778, 2024). "Nonetheless, melanomas with BRAF V600 mutations respond well to current FDA-approved BRAFi, as well as combined BRAF/MEK inhibitor therapy." (PMID 38396984, 2024). "Activating mutations in the BRAF gene are found in approximately 7% of all solid human tumors, particularly common in PTCs, ATCs, and melanomas." (PMID 37985676, 2024). "The V600E mutation of the B-Raf proto-oncogene, a serine/threonine kinase (BRAF), is the most common driver mutation in melanoma patients." (PMID 38775844, 2024). "The phase 2 NeoCombi trial enrolled 35 patients with BRAF V600-mutated melanoma with clinically detectable lymph nodes to receive combination BRAF/MEK inhibition with dabrafenib/trametinib for 12 weeks prior to surgery." (PMID 38500654, 2024). "Among the 24 cancer features frequently found in melanoma cell lines, BRAF mutation was shown to be the most important genomic feature for SB590885 dose–response, and second for drug Dabrafenib and PLX-4720 using the KL-Relevance approach." (PMID 39304771, 2024). "The detailing of the BRAF mutation underlying the melanoma brain metastasis using machine learning-assisted radiomics technique was achieved in contrast to the norm where tissue biopsy is required to determine the genetic aspect of brain metastasis." (PMID 38183141, 2024). "In some other types of tumors, such as melanoma, papillary thyroid carcinoma and colorectal cancer, the association between BRAF mutation and poor survival has been documented." (PMID 38362771, 2024).
melanoma (continued). "We sought to explore if aneuploidy is correlated with PFS for the subset of melanoma patients with the BRAFV600E mutation treated with BRAF-targeted therapy or immunotherapy." (PMID 38473384, 2024). "The BRAF(V600E) mutation has been found in 8%–10% of metastatic colon cancer patients; approximately half of papillary thyroid carcinomas and melanomas exhibit the BRAF(V600E) mutation." (PMID 39052013, 2024). "Matrix metalloproteinase 2 (MMP2) has been identified as a biomarker associated with BRAF mutations and is negatively correlated with survival in patients with BRAF-mutant melanoma, yet its application in clinical practice is limited." (PMID 39336897, 2024). "On a genetic level, melanomas in younger patients are frequently associated with specific mutations, most notably in the BRAF gene." (PMID 39518584, 2024). "All melanoma specimens were tested for BRAF mutations, with the V600 mutations found in 12 out of 22 patients (54.6%)." (PMID 38396984, 2024). "Although BRAF mutations occur in different types of cancer, they are more frequently detected in melanoma." (PMID 39473730, 2024). "The aim of targeted therapies is to inhibit the mitogen-activated protein kinase (MAPK) signaling pathway components, especially in cases of its constitutive activation due to the BRAF V600E mutation, which occurs in approximately 60% of melanomas." (PMID 39797148, 2024). "These drugs focus on inhibiting BRAF V600E, a mutation that is particularly prevalent in melanoma, thyroid cancers, and colorectal cancers." (PMID 38539548, 2024). "In colon cancer cells, dipyridamole augmented the cytotoxicity of the MEK1/2 inhibitor, trametinib, and was used to treat unresectable or metastatic malignant melanomas with BRAF mutations through the dual targeting of the HMGCS1 and MEK pathways." (PMID 38540310, 2024). "For example, dabrafenib in combination with the MEK1/2 inhibitor trametinib was first approved by the FDA in 2014 for the treatment of unresectable or metastatic melanomas with BRAF V600E and V600K mutations." (PMID 38539548, 2024). "As the BRAF inhibitor Vemurafenib was already available for BRAF V600E-mutated melanoma, proof of principle for clinical application in relapsed/refractory HCL was rapidly proven followed by that of Dabrafenib." (PMID 39220131, 2024). "Within Quebec, reflex BRAF testing using real-time polymerase chain reaction (RT-PCR) is completed for all melanomas ≥2 mm in thickness, or those presenting with high-risk features such as ulceration or metastases." (PMID 39661469, 2024). "Activating mutations in the BRAF gene have received widespread attention in the past decade; nearly half of all melanomas have been shown to harbour mutations in BRAF at codon 600, which results in the constitutive activation of the MAPK pathway." (PMID 38333370, 2024). "Key determinants of melanoma behavior (age, tumor location, Breslow thickness, ulceration, mitotic index, and BRAF mutation status) were similar between the oPLND and rPLND group." (PMID 38177461, 2024). "For example, nearly one-half of melanomas arising in the epidermis harbor oncogenic mutations in the BRAF gene, while almost half of the melanomas arising in the uvea harbor oncogenic mutations in the GNAQ/GNA11 genes." (PMID 38360887, 2024). "First identified in 2002, the BRAF mutation has been associated with various malignancies, most commonly melanoma, followed by PTC and colorectal carcinoma." (PMID 39036614, 2024). "Vemurafenib’s mechanism of action involves the selective inhibition of the mutant BRAF protein, with a particular focus on the V600E mutation that is prevalent in approximately 45% of melanoma cases." (PMID 38534309, 2024). "Among the melanoma samples in our study, 12 exhibited BRAF mutations, and 11 had NRAS G12/G13 mutations." (PMID 38396984, 2024). "The internationally quoted incidence of BRAF mutations in melanoma of primary cutaneous origin is 40–71%, including among other predominantly white populations." (PMID 38183457, 2024).
melanoma (continued). "In melanoma patients with BRAF mutations, high ALDH1A3 expression correlates with favorable responses to BRAF/MEK inhibitor therapy." (PMID 39796106, 2024). "Here, we report that the clinically relevant combination of mitogen-activated protein (MAP) kinase pathway inhibitors dabrafenib and trametinib synergize with RIG-I agonist-induced immunotherapy to kill BRAF-mutated human and mouse melanoma cells." (PMID 39165562, 2024). "The most common is the NRAS and BRAF oncogenes, with a high number of melanoma cases demonstrating the BRAF V600 mutation." (PMID 39768392, 2024). "In certain circumstances, autophagy can also promote the occurrence and development of tumors, especially in melanoma with the BRAF V600E mutation, where increased levels of autophagy are associated with the tumor’s resistance to chemotherapy." (PMID 39529955, 2024). "This is reminiscent of our previous project, in which BRAF inhibitors acted as potent ER stress inducers in NRAS-mutated melanoma cells to increase apoptosis rates after MEK inhibition." (PMID 38263136, 2024). "The Tunisian Health Technology Assessment (HTA) body, INEAS, conducted a cost-effectiveness analysis (CEA) of vemurafenib in the treatment of locally advanced or metastatic BRAF V600-mutated melanoma." (PMID 39464179, 2024). "The frequency of BRAF mutations in primary melanomas is commonly reported to be between 40 and 60%, with 54.6% seen in our study." (PMID 38396984, 2024). "Here, we report that TMEM16A/ANO1 is significantly up-regulated in A375 human malignant melanoma cells, which carry the BRAF(V600E) mutation." (PMID 39070550, 2024). "BRAF mutations are widely present in various cancers, including malignant melanoma, thyroid cancer, colorectal cancer, non-small cell lung cancer, and hairy cell leukemia, among others." (PMID 39529955, 2024). "This interim analysis of the MADAM study described the clinical benefits achieved in an adjuvant setting by using D + T in patients with stage III melanoma with BRAF V600 mutation in the real world." (PMID 39682258, 2024). "BRAF is a serine-threonine kinase within the RAS-RAF-MEK-ERK pathway; approximately 50% of melanomas harbor BRAF V600 mutations resulting in constitutive activation of MEK and ERK, with BRAF V600E being the most commonly observed mutation." (PMID 39542696, 2024). "Currently, in the case of advanced melanoma patients, molecular-level assessment of the BRAF mutation status guides the selection of kinase inhibitors." (PMID 39015503, 2024). "Most importantly, in this setting, intratumoral activation of RIG-I synergistically improved the survival of mice carrying BRAF-mutated melanoma." (PMID 39165562, 2024). "Culture of BRAF-mutated melanoma cells in the presence of increasing concentrations of BRAFi can be used to generate BRAFi-resistant cell line variants from BRAFi-sensitive parental cells." (PMID 38755661, 2024). "BRAF V600K-mutated melanomas have dermoscopic features identical to those observed in BRAF V600E-mutated melanomas; furthermore, both groups have a nodular appearance." (PMID 39727691, 2024). "The study supports previous observations, which suggested that inhibition of MAPKs sensitizes BRAF-mutated melanoma cells to RIG stimulation through the induction an IRF1-dependent pro-inflammatory program." (PMID 39165562, 2024). "Conversely, the efficacy and safety profiles of BRAF/MEK inhibitors in the adjuvant setting were retrospectively analyzed in 36 Japanese BRAF‐mutated patients with advanced melanoma." (PMID 38212945, 2024). "A subgroup comparison showed larger numerical differences favoring nivolumab plus ipilimumab in acral melanoma and BRAF-mutant melanomas; nivolumab plus ralatlimab was associated with lower grade 3-4 adverse events compared to nivolumab plus ipilimumab." (PMID 39727691, 2024). "The majority of co-mutated cases had weaker class III BRAF mutations, which have been associated with improved prognosis in melanoma compared with class I BRAF mutations." (PMID 38611025, 2024).
melanoma (continued). "Increased oxidative stress has been linked to BRAF inhibition in melanoma with the BRAF-V600E mutation." (PMID 39501277, 2024). "These mutations are more common (45%) in melanomas that are BRAF and RAS wild-type (WT), and they are associated with a high number of inactivating mutations, including splice variants, early termination, and insertion–deletion (InDels)." (PMID 39126091, 2024). "The fact that some ERK-associated cancers, such as BRAF mutant melanoma, are sensitive to ERK activation is well-established." (PMID 38485987, 2024). "Mutations in BRAF have also been linked with human carcinogenesis, where an increased level of BRAF mutations was observed in ovarian carcinoma, colorectal carcinoma, and melanomas." (PMID 39558949, 2024). "There was a positive correlation between the mRNA levels of ICAM1 and the presence of BRAF mutations, which are among the most common genetic alterations in melanoma (r = 0.23, p < 0.001)." (PMID 38874532, 2024). "Recent studies indicate that the V600K mutation is the second most common BRAF mutation in melanoma, representing approximately 20–30% of BRAF mutant melanoma tumors." (PMID 38534309, 2024). "The patient was treated for BRAF-mutated malignant melanoma of the temporoparietal head region with metastasis of adjacent skin and neck lymph nodes solved surgically by radical dissection." (PMID 39583362, 2024). "About 50% of melanomas contain activating BRAF mutations, the most common of which is the V600E mutation, which leads to the constitutive activity of downstream MAPK signaling." (PMID 38203846, 2024). "BRAF mutations constitute the most common genetic mutation present in about 50% of melanoma patients, but mutated BRAF is also detected in melanocytes." (PMID 38672652, 2024). "At the molecular level, melanoma is driven by genetic mutations in key regulatory genes, including BRAF, NRAS, and c-KIT, which are implicated in cell growth, differentiation, and survival pathways." (PMID 39598801, 2024). "The vast majority of melanomas are sporadic, and one of the more common molecular alterations is the mutation of the BRAF gene." (PMID 38667446, 2024). "The two most common forms of BRAF mutations among patients with BRAF-mutant melanoma are the V600E and V600K mutations, with the former found in 70–90% of these patients." (PMID 39336897, 2024). "For melanoma brain metastases with BRAF V600 mutations, a combination therapy with dabrafenib and trametinib is effective; however, the responses are less durable than those of extracranial metastases with the same mutations." (PMID 39204387, 2024). "Herein, our study uncovers the novel role of laminB1 in regulating the response of BRAF-mutated melanoma cells to BRAFi PLX4720 (vemurafenib)." (PMID 39682248, 2024). "Raj and co-workers described a jackpot effect, whereby a stochastic combination of non-mutational (i.e., epigenetic) events generate rare cells in BRAF-mutant melanoma cultures under BRAFi." (PMID 39001489, 2024). "Among the melanoma cell lines analyzed, three, Mel Il, Mel Ibr, and Mel Z, harbored hyperactivating mutations in the BRAF gene, while one, Mel Mtp, carried a mutation in the NRAS gene." (PMID 39772250, 2024). "Primary melanomas with BRAF V600E mutations indeed had more frequent inactivating mutations of the CDKN2A gene (45.2 vs. 27.7%, P = 0.027, Fisher's exact test), consistent with early corruption of critical cell-cycle checkpoint components triggered by OIS." (PMID 38371417, 2024). "We next examined the functional role of PEDF directly, particularly in the context of melanoma wherein NF1 mutations are associated with more invasive disease in both BRAF mutant and wild type disease." (PMID 39355740, 2024).